NANOG (Nanog homeobox)
Description:
Transcription regulator involved in inner cell mass and embryonic stem (ES) cells proliferation and self-renewal. Imposes pluripotency on ES cells and prevents their differentiation towards extraembryonic endoderm and trophectoderm lineages. Blocks bone morphogenetic protein-induced mesoderm differentiation of ES cells by physically interacting with SMAD1 and interfering with the recruitment of coactivators to the active SMAD transcriptional complexes. Acts as a transcriptional activator or repressor. Binds optimally to the DNA consensus sequence 5'-TAAT[GT][GT]-3' or 5'-[CG][GA][CG]C[GC]ATTAN[GC]- 3'. Binds to the POU5F1/OCT4 promoter. Able to autorepress its expression in differentiating (ES) cells: binds to its own promoter following interaction with ZNF281/ZFP281, leading to recruitment of the NuRD complex and subsequent repression of expression. When overexpressed, promotes cells to enter into S phase and proliferation.
Synonyms: FLJ12581; FLJ40451
Tractability: No criterion of Open Targets' tractability assessment is met for any kind of drug.
Target class: Transcription factor
Gene: Protein-coding gene on chromosome 12 (7,787,794 to 7,799,146, forward strand). Ensembl gene ENSG00000111704.
Subcellular location: Nucleus
Subcellular location (Human Protein Atlas): Nucleoplasm
Pathways (Reactome):
Developmental Biology: Formation of the anterior neural plate; Germ layer formation at gastrulation; POU5F1 (OCT4), SOX2, NANOG activate genes related to proliferation; POU5F1 (OCT4), SOX2, NANOG repress genes related to differentiation; Transcriptional regulation of pluripotent stem cells
Immune System: Interleukin-4 and Interleukin-13 signaling
Reproduction: Specification of primordial germ cells
Gene Ontology:
Molecular function: DNA binding; DNA-binding transcription factor activity; protein binding; RNA polymerase II transcription regulatory region sequence-specific DNA binding; sequence-specific double-stranded DNA binding; transcription cis-regulatory region binding; DNA-binding transcription factor activity, RNA polymerase II-specific; DNA-binding transcription repressor activity, RNA polymerase II-specific; RNA polymerase II cis-regulatory region sequence-specific DNA binding
Biological process: cell differentiation; endodermal cell fate specification; positive regulation of stem cell proliferation; positive regulation of transcription by RNA polymerase II; regulation of cell differentiation; regulation of DNA-templated transcription; regulation of gene expression; somatic stem cell population maintenance; stem cell population maintenance; regulation of transcription by RNA polymerase II; negative regulation of transcription by RNA polymerase II; positive regulation of cell population proliferation
Cellular component: nucleolus; nucleoplasm; nucleus; chromatin
Genetic constraint (gnomAD): Loss-of-function variants: 2 observed, 15.73 expected, observed/expected ratio (o/e) 0.13, 90% interval 0.051 to 0.4. The upper end of that interval is the gene's LOEUF score, 0.4, which puts it in group 1 of 6, group 1 being the genes least tolerant of losing a copy. Missense variants: 155 observed, 232.45 expected, observed/expected ratio (o/e) 0.67, 90% interval 0.58 to 0.76. Synonymous variants: 70 observed, 81.39 expected, observed/expected ratio (o/e) 0.86, 90% interval 0.71 to 1.05.
Homologues: Orthologues: chimpanzee NANOG (98% identical), macaque NANOG (94% identical), pig NANOG (76% identical), dog NANOG (69% identical), rat Nanog (62% identical), mouse Nanog (57% identical), zebrafish nanog (22% identical), Caenorhabditis elegans ceh-43 (17% identical), Drosophila melanogaster Dll (16% identical). Paralogues in human: NANOGP8 (99% identical), DLX5 (19% identical), DLX3 (18% identical), DLX6 (18% identical), DLX1 (18% identical), DLX4 (17% identical), DLX2 (16% identical), VENTX (15% identical), BSX (14% identical).
Diseases named in the same sentence as NANOG in open-access papers:
NANOG is named in the same sentence as 198 diseases in open-access papers, as found by Europe PMC text mining. Sharing a sentence is not in itself a finding about the gene and the disease. The quoted sentences say what the papers report.
breast carcinoma (228 papers, 2006 to 2025). "NANOG expression is closely associated with the stem cell characteristics, invasiveness, and apoptosis of breast cancer, and reducing its expression can decrease the proportion of BCSCs and their self-renewal capacity." (PMID 39605916, 2024). "The expression signatures of OCT4, SOX2, and NANOG are associated with poor clinical outcomes in breast cancer." (PMID 34064635, 2021). "Here we report that exposure of breast cancer cells to hypoxia also induces ZNF217-dependent inhibition of m6A methylation of mRNAs encoding NANOG and KLF4, which is another pluripotency factor that mediates BCSC specification." (PMID 27590511, 2016). "Increased NANOG expression is associated with poor prognosis in various cancers, such as lung cancer, oral cancer, brain cancer, ovarian cancer, breast cancer, and prostate cancer." (PMID 26087476, 2015). "NANOG has also been associated with poorer overall survival of breast cancer patients, suggesting a relationship between NANOG expression and tumour grade." (PMID 26580604, 2015). "Re-expression of the embryonic stem cell and pluripotency factors OCT4, SOX2, and NANOG has been associated with poorly differentiated and aggressive cancers, such as high-grade breast cancer, glioblastomas, and bladder carcinomas." (PMID 22911243, 2012). "GASC1 demethylase activity has been shown to regulate the expression of genes critical for stem cell self-renewal, including NOTCH1 and NANOG, and possibly to be linked to the stem cell phenotypes in breast cancer." (PMID 23148692, 2012). "Indeed, aberrant expression of BORG in mouse and human breast cancers was associated with the acquisition of breast cancer stem cell-like properties and upregulation of known breast cancer stem cell markers, such as NANOG, ALDH1, and ITGA6/α6Integrin/CD49f." (PMID 39335212, 2024). "Namely, LEF1 is part of the Wnt/β-catenin signaling pathway, which includes for example genes such as c-Myc, LBH, Oct4, NANOG that have been associated with the upregulation of proteins typically involved in human breast cancer, gastrointestinal tumors, prostate cancer, leukemia, and others." (PMID 38003292, 2023). "The researchers have also reported that the exposure of breast cancer cells to hypoxia induces zinc finger protein 217 (ZNF217)-dependent inhibition of m6A methylation of mRNAs encoding NANOG and Kruppel-like factor 4 (KLF4), which is another pluripotency factor that mediates BCSC speciation." (PMID 29587823, 2018). "Notably, up-regulation of m6A demethylase ALKBH5 induced by hypoxia causes mRNA demethylation of stem cell marker NANOG, leading to increased NANOG expression and tumor initiation capacity of breast cancer stem cells." (PMID 30212448, 2018). "Mechanistically, we demonstrated that MUC16-Cter results in nuclear translocation of JAK2, which preferentially phosphorylates histone-3 and up regulates stemness-specific genes such as LMO2 and NANOG, which was further validated using Jak2 deficient (Jak2−/−) mouse mammary tumor cells." (PMID 25691062, 2015). "In various cancer types, NANOG exerts a pro-tumorigenic action associated with either cancer growth promotion, as observed in human gastric cancer cells, glioblastomas, and breast cancer cells, or enhanced invasiveness and malignancy, as observed in breast cancer and hepatic tumors." (PMID 32197405, 2020). "The expression of OCT-4 has further been shown in human breast cancer stem-like cells, implicating its involvement in tumorigenesis and self-renewal by activating its downstream target genes, such as NANOG and SOX2." (PMID 41376750, 2025). "To confirm that KIF20A regulates breast cancer stemness, we assessed the expression of canonical stem cell markers (Oct4, Sox2, or NANOG) and found that KIF20A siRNA transfection led to decreased mRNA levels of these markers in Hs578T cells." (PMID 41392981, 2025).
breast carcinoma (continued). "Immunostaining with anti-YAP/TAZ, anti-C1orf50, and anti-NANOG antibodies in tissue arrays showed that C1orf50-high breast cancer cells express YAP/TAZ and NANOG at high levels in Luminal breast cancer cells." (PMID 39604563, 2025). "Roc-A can suppress the self-renewal ability of breast cancer stem cells by decreasing the expressions of Nanog homeobox (NANOG) and Octamer binding protein-4 (OCT4)." (PMID 40005151, 2025). "NANOG is expressed in a variety of human malignancies, particularly breast cancer, colon cancer, head and neck cancer, lung cancer and pancreatic cancer." (PMID 40272007, 2025). "In breast cancer, hypoxia-inducible factor 1α (HIF1α) and HIF-2α stimulate the expression of ALKBH5 which can demethylate NANOG mRNA and increase its stability, inducing the breast cancer stem cell (BCSC) phenotype." (PMID 40483535, 2025). "The combined treatment induces G2/M cell cycle arrest and disrupts the physical association of CD44 with NANOG and MDR1 in MDA-MB-231 cells, thus overcoming breast cancer resistance and promoting cancer cell death." (PMID 39519572, 2024). "ALKBH5‐dependent approach induces increased NANOG mRNA and protein expression and breast cancer stem cell phenotype." (PMID 39006762, 2024). "The exposure of breast cancer cells to hypoxia increased NANOG mRNA and protein expression and induced BCSC phenotype by a hypoxia-inducible factor (HIF)- and ALKBH5-dependent manner." (PMID 38254782, 2024). "Further exploration of the mechanisms by which NANOG cooperates with METTL14 to maintain breast cancer stemness is necessary to answer this question." (PMID 39563370, 2024). "According to TCGA data for breast cancer, TSP50 mRNA expression was positively correlated with OCT4, ALDH1, NANOG and CD44 markers associated with BCSC." (PMID 39030572, 2024). "Research exposed that MYC combined with SLUG promoter activated the transcription, which increased the expression of OCT4 and NANOG, and enhanced the characteristics of CSCs in breast cancer." (PMID 38561775, 2024). "In breast cancer, ALKBH5 expression is induced by hypoxia‐inducible factor 1α (HIF1α) and HIF1β, and its overexpression under hypoxic conditions reduces NANOG mRNA methylation levels, increasing the number of breast cancer stem cells." (PMID 39445003, 2024). "A recent study revealed that hypoxia tumor microenvironment increased ALKBH5 expression, which eliminated m6A modified NANOG and enhanced its mRNA stability, thereby promoted breast cancer stem cell phenotype 46." (PMID 37283789, 2023). "To evaluate the therapeutic value of TAZ and NANOG in vivo, we established a mouse xenograft model of breast cancer." (PMID 36646707, 2023). "SOX2, NANOG, OCT3/4, as well as a CD44+/CD24−/low phenotype were reported to be the principal markers associated with stemness in breast cancer." (PMID 37446326, 2023). "KLF8 regulated mRNA and protein levels of CSCs markers, including OCT4, SOX2, MYC and NANOG in breast cancer cells." (PMID 37152043, 2023). "Specifically, KDM1B, also referred to as lysine-specific demethylase 2 (LSD2), promotes the proliferation of MDA-MB-231 breast cancer cells and induces the expression of pluripotent stem cell markers NANOG and SOX2." (PMID 37761999, 2023). "Hypoxia induces ALKBH5 expression in breast cancer cells, which reduces the m6A modification of NANOG and promotes the initiation and metastasis of breast cancer." (PMID 36536402, 2022). "ALKBH5-mediated m6A-demethylation of NANOG mRNA is involved in hypoxia-induced breast cancer stem cell phenotype." (PMID 35595748, 2022). "In 2016, research showed that ZNF217 inhibited the m6A methylation of KLF4 and NANOG mRNA, which was catalyzed by METTL3 and resulted in elevated KLF4 and NANOG protein levels, which in turn promoted the progression of breast cancer." (PMID 35945641, 2022).
breast carcinoma (continued). "Abnormal expression of NANOG has been reported in human cancers, such as breast cancer, cervical cancer, or brain cancer, suggesting the implication of Nanog in tumourigenesis and cancer progression." (PMID 36566021, 2022). "Although a study on breast cancer reported that NFRSF17 can act as a co-receptor of ALDH1A1, KLF4 and NANOG, mediating their tumour-promoting effects in breast cancer." (PMID 36203424, 2022). "Expected staining patterns were demonstrated in control human tissues: seminoma for OCT4, normal skin for SOX2, seminoma for NANOG, breast cancer for KLF4 and normal prostatic tissue for c-MYC." (PMID 34685477, 2021). "NANOG expression has also been correlated with poor prognosis and promotes breast cancer tumorigenesis and metastasis." (PMID 34638956, 2021). "Upregulation of ALKBH5 was shown to contribute to breast cancer initiation by attenuating NANOG mRNA methylation and thereby increasing NANOG expression under hypoxia." (PMID 34616742, 2021). "CXCL12 overexpression induces EMT in breast cancer cells, activating stem cell-associated genes like SOX2, OCT4, and NANOG, promoting a stem-like phenotype marked by ALDH1 expression and Wnt/β-catenin pathway activation." (PMID 33530455, 2021). "ALKBH5 overexpression induced by HIF1A reduces the methylation of NANOG mRNA, leading to increased expression of NANOG and breast cancer stem cells." (PMID 33430133, 2021). "A recent comparative analysis demonstrated that in patients with breast cancer, a hypomethylation signature (OCT4, SOX2, NANOG and SIN3A) in CTC clusters is associated with poor progression-free survival." (PMID 34830995, 2021). "In contrast, hypoxia induces m6A-demethylation of NANOG mRNA in a HIF- and ALKBH5-dependent manner to cause breast cancer stem cell phenotype." (PMID 34491904, 2021). "Under non-hypoxic conditions, ALKBH5 promotes mRNA stability and expression of NANOG by catalyzing m6A demethylation, thus leading to the enrichment of breast cancer stem cells." (PMID 34900723, 2021). "NANOG induction promoted drug resistance in the breast cancer cell line MCF-7, and tumor regeneration and resistance to androgens starvation in the prostate cancer cell lines Du145 and LNCaP." (PMID 34638956, 2021). "NANOG induction in association with WNT1 pathway induces tumorigenesis in murine mammary gland and enhances mammary tumour metastasis." (PMID 34203746, 2021). "ALKBH5 upregulation showed decreased m6A level in pluripotency induction marker NANOG mRNA in breast cancer stem cells (BCSCs)." (PMID 32194861, 2020). "LINC00511 has been implicated in breast cancer tumorigenesis and stemness through modulation of the miR-185-3p/E2F1/NANOG axis." (PMID 32244924, 2020). "The inhibition of NANOG expression can decrease the proliferation of breast cancer stem cells and esophageal cancer stem cells, thereby impeding the formation of cancer cell colonies." (PMID 33336042, 2020). "In this study, we reveal that mTOR inhibitors unexpectedly induce breast cancer cell plasticity by enabling the translation of NANOG, SNAIL, and NODAL isoforms in a manner similar to hypoxia." (PMID 32427827, 2020). "We report that in breast cancer cells NANOG, SNAIL and NODAL transcripts manifest multiple isoforms characterized by different 5’ Untranslated Regions (5’UTRs), whereby translation of a subset of these isoforms is stimulated under hypoxia." (PMID 32427827, 2020). "Similar result was also observed in breast cancer cells where ALKBH5-mediated m6A demethylation of NANOG mRNA enhanced the breast cancer stem cell (BCSC) in hypoxic condition." (PMID 32194861, 2020). "Stem cell-associated proteins, including NANOG, SNAIL, and NODAL, have been shown to induce epithelial to mesenchymal transition (EMT) and are associated with poor outcomes in breast cancer patients." (PMID 32427827, 2020).
breast carcinoma (continued). "Herein, we demonstrate that breast cancer cells possess multiple transcript isoforms of NANOG, SNAIL, and NODAL that differ in their 5′UTRs, some of which show preferential translation in hypoxia facilitating increased protein expression." (PMID 32427827, 2020). "LncRNA-HAL is located in the intronic region in the MNT gene and its expression is correlated with expression of stemness factors such as CD44, CD24 and NANOG in breast cancer." (PMID 32244924, 2020). "Recent researches noted that ALKBH5 up-regulated the expression of NANOG by demethylating m6A and promoted the gathering of breast cancer cells in the tumor microenvironment." (PMID 32742194, 2020). "Hypoxia-inducible factor (HIF)-1α-and HIF-2α-dependent ALKBH5 in breast cancer cells can be stimulated under hypoxia condition, leading to demethylation of NANOG mRNA." (PMID 33362863, 2020). "ALKBH5 promoted cancer cell renewal and growth in breast cancer by removing m6A from NANOG mRNA, which in turn enhanced NANOG mRNA stability and pluripotency of cancer cells." (PMID 32111213, 2020). "ALKBH5 promoted renewal and growth of breast cancer cells by reversing m6A of NANOG mRNA, which in turn enhanced the stability of NANOG and stemness of cancer cells." (PMID 32209098, 2020). "The increased NANOG protein levels promote the enrichment of breast cancer stem cell (BCSC) population." (PMID 32091154, 2020). "With the development of research, NANOG has been found highly expression in breast cancer, spermatogonioma, gastric cancer, intestinal cancer, cervical cancer, oral squamous cell cancer and pancreatic cancer, and so on." (PMID 31147453, 2019). "Hypoxia-induced ALKBH5 expression in breast cancer cells enhances mRNA stability of homeobox transcription factor NANOG and induces its overexpression, leading to a phenotype specific to breast cancer stem cells." (PMID 30654440, 2019). "For instance, the m6A demethylase ALKBH5 was reported to induce the breast cancer stem cell phenotype by demethylating NANOG mRNA, whereas a later study revealed an important role of ALKBH5 in inhibiting the progression of pancreatic cancer." (PMID 31607270, 2019). "The mechanism by which NRF1 drives the expression of embryonic pluripotency transcription factors, OCT4, SOX2, and NANOG necessary for maintaining breast cancer cell stemness remains to be determined." (PMID 30486409, 2018). "Aberrant expression of NANOG has been previously found in a variety of tumors, including breast cancer." (PMID 29963272, 2018). "Expression of NANOG in CSCs is detected in a variety of cancer types, including glioma, breast cancer, ovarian cancer, and lung cancer." (PMID 29971070, 2018). "In MDA-MB-231 breast cancer cells, the knockdown of the eraser ALKBH5 caused the demethylation of m6A in NANOG mRNA and significantly decreased metastasis from breast to lungs in immunodeficient mice." (PMID 29958477, 2018). "Positive controls were human seminoma for OCT4 (pink, arrows), normal skin for SOX2 (pink, arrows), seminoma for NANOG (pink, arrows), breast cancer for KLF4 (pink, arrows), and normal prostate for c-Myc (pink, arrows)." (PMID 29404335, 2017). "Expression of stemness-related genes including SOX2 and NANOG confirmed that mammosphere-forming culture of breast cancer cells enriched BCSC-like cells." (PMID 28703799, 2017). "Upregulation of ALKBH5 also induced the loss of m6A in NANOG mRNA, which in turn increased its stability and NANOG protein levels in breast cancer stem cells (BCSCs)." (PMID 28533023, 2017). "In the present study, hypoxia induced the HIF-dependent enrichment of BCSCs in all breast cancer cell lines, which was accompanied by increased expression of one or more pluripotency factors (NANOG, KLF4, or SOX2)." (PMID 27590511, 2016). "NANOG is expressed in various cancers, such as ovarian cancer, breast cancer, colorectal cancer, and prostate cancer, and it is enriched in CSCs." (PMID 26087476, 2015).